C3 (complement C3)
Diseases named in the same sentence as C3 in open-access papers (continued):
Sharing a sentence is not in itself a finding about the gene and the disease.
lupus (continued). "Serum low levels of complement C3, C4 and CH50 as indicators of lupus activity have been included in the Systemic Lupus Erythematosus Disease Activity Index 2000 scoring system (Gladman, Ibanez & Urowitz, 2002)." (PMID 36420131, 2022). "While in remission afterwards, C3 and CH50 serum levels were found to be low, but C4 serum levels were normal and lupus anticoagulant as well as anti-phospholipid antibodies were negative." (PMID 35615072, 2022). "Classic biomarkers of lupus activity such as anti-ds DNA, UACR, C1q, C3 and C4 complement proteins were assessed." (PMID 34442337, 2021). "To identify the upstream and downstream relationships of these upregulated genes (C1q, C3, C3aR1, C5aR1, CR3, and CR4), we performed KEGG pathway analysis using the lupus mouse microarray database." (PMID 34433493, 2021). "C3, CFH, SERPING1, FGA, and FGG were significantly enriched in the “complex and coagulation cascades pathway,” C3 was also enriched in the “systemic lupus erythematosus” pathway, and PRB1 in the “salivary secretion” pathway." (PMID 34516718, 2021). "This is the first report to show that the combination of pre-pregnancy serum C3 level and a history of lupus nephritis may predict preterm birth in pregnancies with SLE." (PMID 33980284, 2021). "The IF staining results indicated that lupus IgG1-injected MRL-lpr/lpr mice exhibited significantly less deposition of C1q, C3, IgG, IgG1, and IgG3 within their glomeruli at 19 weeks of age compared with that of control IgG1-treated and non-treated groups." (PMID 32625200, 2020). "They found that TCV was associated with remissions in clinical symptoms, reductions in Systemic Lupus Erythematosus Disease Activity Index (SLEDAI) and anti-ds-DNA antibodies, and increases in complement component 3 (C3) and C4." (PMID 32477335, 2020). "Furthermore, with the use of the assay for human C3 fragments, we observed that patients with systemic lupus erythematosus (SLE) (n = 144) had significantly higher iC3b/C3dg levels as compared to healthy individuals (n = 144) (p < 0.0001)." (PMID 32431705, 2020). "Immunofluorescence analysis showed massive pathological IgG and C3 deposits in the glomeruli in the mice of CD39− and ARL groups that were similar to the lupus group, while markedly decreased deposition was seen in the CD39+ treatment mice." (PMID 31402273, 2019). "In lupus (SLE) patients, patients with the 2/2 genotype had reduced disease activity, as measured by reduced renal involvement and higher C3 levels." (PMID 29559979, 2018). "KEGG analysis revealed the systemic lupus erythematosus pathway involving CD86, TNF, C4, FCGR2B, CD80, C3, CD40, and C1S." (PMID 28976997, 2017). "There were significant correlations between serum PTX3 levels and Systemic Lupus Erythematosus Disease Activity Index (SLEDAI) scores, serum creatinine value, renal pathological activity indices, and serum complement 3 (C3) in active lupus nephritis patients." (PMID 26817892, 2016). "Antibody titer is correlated with European Consensus Lupus Activity Measurement (ECLAM) score and anti-complement component 1q (C1q) antibodies, negatively with C3 levels." (PMID 27716380, 2016). "Results from a phase 2 study in patients with systemic lupus erythematosus (SLE) were encouraging, with significant reductions in disease biomarkers, including circulating levels of autoantibodies and marked increases in C3 levels." (PMID 26335795, 2015). "The patient met criteria for systemic lupus erythematosus (SLE) based on Lupus International Collaborating Clinics Classification criteria due to positive ANA titer, positive anti-dsDNA, low C3 and C4 levels, and thrombocytopenia and renal involvement." (PMID 25544909, 2014). "This variant was previously reported in homozygosity in a 19-year-old Turkish AGS patient with lupus-like features: chilblain lesions on feet, oral ulcers, ANA (antinuclear antigens), anti-ENA (extractable nuclear antigens), and decreased C3 levels." (PMID 24224166, 2013).
lupus (continued). "One-sample Kolmogorov-Smirnov test was used to evaluate distribution of age, IL-18, sFas, C3, C4, ESR, anti-dsDNA, and 24-hour urine protein excretion parameters in three groups including all participants, severe lupus, and mild lupus separately." (PMID 23577265, 2013). "C3 and C4 are usually decreased in the setting of active lupus, due to immune complex formation, but they may be normal in preeclampsia, HELLP, or aHUS despite ongoing complement activation (since C3 and C4 are also acute phase proteins)." (PMID 40777009, 2025). "Intriguingly, we did not observe C3 or C4 consumption in patients with irAE-n, in contrast to other immune-mediated diseases such as systemic lupus erythematosus (SLE)." (PMID 40506552, 2025). "While our data found a classical engagement of C3 with C3 and C4, nidogen-1 (NID1), and plasminogen (PLG), C3-LHF1 also engaged with other lupus- and autoimmune-related proteins, such as WDR1, RPL22, and PXDN, supporting its mechanism of interacting with surface binders." (PMID 41145914, 2025). "The analysis of serological samples from 65 SLE patients revealed a positive correlation between IFN-I levels and the Systemic Lupus Erythematosus Disease Activity Index (SLEDAI) score and anti-dsDNA levels and inversely correlated with complement 3 (C3) levels." (PMID 39478861, 2024). "Conventional investigations such as lupus serological tests to assess anti-dsDNA and C3 levels reflect immunological status but not organ injury, and their change over time is useful in many but not all patients." (PMID 39411720, 2024). "In cases of typical clinical picture, but non-diagnostic histopathological picture, the lupus band test (LBT) is recommended and deposits of immunoglobulins or C3 at the dermo-epidermal junction, detected in 70–90% of cases, support the diagnosis." (PMID 38673692, 2024). "Whilst there was strong colocalisation of DNASE1L3 and C1Q, and to some extent C3 and C1R, there was no colocalisation between DNASE1L3 and the other lupus related genes, including genes associated with apoptosis." (PMID 38744839, 2024). "Disease activity parameters included Systemic Lupus Erythematosus Disease Activity Index 2000 (SLEDAI-2K) score, erythrocyte sedimentation rate, C-reactive protein level, anti-double strain DNA antibody level, complement fractions C3 and C4 levels." (PMID 38562920, 2024). "Intracellular C3 system dysregulation contributes to human autoimmune diseases such as scleroderma, systemic lupus erythematosus (SLE), RA, and multiple sclerosis, as pathological intracellular C3 hyperactivation contributes to Th1 hyperactivity in these autoimmune conditions." (PMID 36969185, 2023). "Although it is becoming more commercially available, neither functional C assays nor individual plasma C components other than C3 and C4 are routinely used by most experienced lupus clinicians." (PMID 37153614, 2023). "Renal IFI16 expression was positively associated with systemic lupus erythematosus disease activity index (SLEDAI) and serum creatinine while negatively related to baseline eGFR and serum complement C3." (PMID 37393341, 2023). "The patients had systemic Lupus Erythematosus Disease Activity Index 2000 (SLEDAI-2K) score, levels of antidouble-stranded DNA antibody, complement components C3 and C4, 24-hour proteinuria and corticosteroid reduction were recorded at baseline and at 6, 12, and 18 months." (PMID 36401486, 2022). "Anti-dsDNA, C3, C4 and urinalysis normalized while anti-Smith and Sjögren antibodies persisted 15 months after disease onset, with no other lupus manifestations." (PMID 35372162, 2022). "IgA, IgG, IgM, C3 and C1q deposits were simultaneously present without clinical signs of systemic lupus erythematosus (SLE) and with negative autoantibody serology (ANA, anti-DNA antibodies, ANCA)." (PMID 34919149, 2022).
lupus (continued). "Immunofluorescence staining in the kidney revealed that IgG and C3 immune deposition in the glomeruli and interstitium was similarly increased in the sodium chloride group compared to that of control-pretreated BMDC-ALD-DNA-induced lupus mice." (PMID 32296043, 2020). "Actually, the patients we enrolled were well-characterized pediatric-onset lupus with consistent gender distribution, typical clinical features, and bona fide flares by the significant differences in SLEDAI, serum C3 and C4, anti-dsDNA, and hematologic features in active phase." (PMID 29492211, 2018). "Additionally, variations in the C3 gene have been associated with several inflammatory diseases, such as age-related macular degeneration (AMD), polypoidal choroidal vasculopathy (PCV), systemic lupus erythematosus (SLE), and inflammatory bowel disease." (PMID 28408754, 2017). "There was not any statistical difference between following items in lupus patients with and without MetS: serum levels of C3 (P=0.1), C4 (P=0.2), anti anti-DNA/R (p=0.8) as well as frequency of organ involvement (P=0.3)." (PMID 27757205, 2016). "On univariate analyses, presence of disease damage (SDI ≥ 1)was significantly associated with older age, longer disease duration, neuropsychiatry lupus (NPSLE), APLS, positive LA,use oral prednisolone more than 1mg/kg daily over more than 2 weeks, and lower cumulative C3 levels (p<0.05)." (PMID 27846298, 2016). "While C1q deficiency results in development of lupus in virtually all cases, absence of C3, C2, and C4 results in lupus at lower frequency indicating a role for C1q beyond classical complement pathway activation in regulation of the immune response." (PMID 25191325, 2014). "The aim of this study was to analyze the changes in complements C3 and C4 and C-reactive protein (CRP) in patients with systemic lupus erythematosus (SLE) and rheumatoid arthritis (RA), and to evaluate the role of these indices in the differential diagnosis of SLE and RA." (PMID 24223657, 2013). "Bullous systemic lupus erythematosus is characterized by linear or granular IgG/IgA patterns, and C3, and can be positive or negative for IgM along the basement membrane." (PMID 23110919, 2012). "In this paper we describe complement C3 and C4 deposition patterns in control non-autoimmune subjects and lupus patients in the active and inactive phase of the disease and demonstrate the utility of such measurements." (PMID 22984570, 2012). "The systemic lupus erythematosus disease activity index (SLEDAI), the validated activity index, frequently used for assessing global SLE activity, includes the presence of low complements, that is the decrease in CH50, C3, or C4 in qualitative assessment." (PMID 36830735, 2023). "As an example, C3d is a robust marker for C3 activation, extensively studied in complement-mediated diseases such as age-related macular degeneration (AMD) or Systemic lupus erythematosus (SLE)." (PMID 36420270, 2022). "We found that the expression of circIBTK was downregulated in SLE and correlated with Systemic Lupus Erythematosus Disease Activity Index (SLEDAI) score, anti-double-stranded (ds)DNA and complement C3 level in patients with SLE." (PMID 29884225, 2018). "Fifth, we did not use serum titers of C3 and C4 to assess lupus flare during pregnancy." (PMID 26295404, 2015). "Diagnosis of lupus lesions in patients with skin rashes is determined by a clinical test using direct immunofluorescence (DIF) to detect immunoreactants, most commonly immunoglobulin G (IgG), IgM, IgA, and complement component 3 (C3), along the dermal-epidermal junction." (PMID 23940681, 2013). "Plasma MBL correlated with systemic lupus erythematosus disease activity index (SLEDAI) (P = 0.0003, r = 0.36), anti-dsDNA (P < 0.0001, r = 0.54), proteinuria (P < 0.0001, r = 0.42) and negatively correlated with C3 (P = 0.007, r = -0.27) and C4 (P = 0.01, r = -0.29)." (PMID 23068019, 2012).
lupus (continued). "Moreover, uTWEAK performed significantly better than traditional biomarkers in widespread use (anti-dsDNA Abs, C3 and C4) in distinguishing between lupus patients with and without nephritis." (PMID 19785730, 2009). "In addition, lupus IgG1, but not control IgG1, increased serum C3 and complement factors B levels, decreased serum IFN-γ and IL-17 levels, as well as decreased serum creatinine and BUN levels in MRL-lpr/lpr mice by a dose-dependent manner within a range of 0.5 mg to 3.0 mg per mouse in vivo." (PMID 32625200, 2020). "As noted, up to one-half of SLE patients will present with serum C4 and C3 in a normal range, which obviously does not rule out a lupus diagnosis." (PMID 26913032, 2016). "Immunofluorescence showed a “full‐house” pattern (IgG, IgA, IgM, C3, and C1q) in the absence of systemic lupus erythematosus (SLE) features (negative ANA, normal C3)." (PMID 41476811, 2026). "Both AAE and systemic lupus erythematosus (SLE) can present with reduced C1q levels; however, in SLE this is typically accompanied by low C4 and C3 due to classical complement pathway activation, whereas in AAE only C1q and C4 are usually decreased, with C3 remaining normal." (PMID 40629920, 2025). "Weekly treatment with intravenous HGC-TAC improved all these parameters, albeit serum blood urea nitrogen and C3 levels were not significantly different between vehicle- or TAC-treated lupus mice and HGC-TAC-treated lupus mice." (PMID 33865397, 2021). "Higher titers of circulating antibodies, low C3, C4 and CH50 and increased deposition of immune complexes in tissues are seen during lupus activity, especially on those who develop LN, tending to normalize with clinical improvement." (PMID 33841392, 2021). "In clinical practice, the assessment of disease activity in SLE is performed by means of disease activity scores Systemic Lupus Erythematosus Disease Activity Index 2000 (SLEDAI-2K) or additional testing for the complement components 3 and 4 (C3, C4) and anti-dsDNA titers." (PMID 32772131, 2020). "The fact that low complement is listed as a Systemic Lupus Collaborating Clinics classification criterion only to reflect the contribution of complement to SLE pathogenesis, but that it did not improve statistical modeling, further indicates that C3 and C4 are not optimal markers for monitoring SLE." (PMID 29208014, 2017). "UBE2L3 genotype was not correlated with blood markers of lupus activity including ESR, low serum complement C3 and C4 levels, or anti-dsDNA antibody or anti-nuclear antibody titer." (PMID 25640675, 2015). "Remarkably, all uEV size-subset concentrations displayed significant positive and strong correlations with the Systemic Lupus Erythematosus Disease Activity Index (SLEDAI), and most of them also exhibited strong but negative correlations with serum concentration of the complement C3 subunit." (PMID 39451594, 2024). "Non‐lupus full‐house nephropathy (FHN) is a rare and exciting renal pathology defined by the presence of a full‐house immunofluorescence pattern‐deposition of IgG, IgA, IgM, C3, and C1q‐in the absence of systemic lupus erythematosus (SLE) clinical or serological criteria." (PMID 41476811, 2026). "HC: Healthy Control; non-NPSLE: Non-neuropsychiatric Systemic Lupus Erythematosus; SLEDAI: Systemic Lupus Erythematosus Disease Activity Index; SDI: Systemic Lupus International Collaborating Clinics /American College of Rheumatology (SLICC/ACR) Damage Index; Serology: C3, C4 and CH50." (PMID 38807248, 2024). "In particular, in SLE patients, serum HMGB1 levels correlated with systemic lupus erythematosus disease activity index (SLEDAI), proteinuria, and anti-ds-DNA antibodies, showing a negative correlation with complement C3." (PMID 29410969, 2017).
lupus (continued). "Currently, SLE was adequately controlled (Systemic Lupus Erythematosus Disease Activity Index, SLEDAI = 0, anti-dsDNA antibodies negative, C3 and C4 levels normal); medication included methylprednisolone 8 mg/day, azathioprine 50 mg/day, aspirin 50 mg/day and levothyroxine 150 μg/day." (PMID 22206235, 2011).
COVID-19 (177 papers, 2020 to 2025). A disease caused by infection with severe acute respiratory syndrome coronavirus 2. "In patients with severe COVID-19, lower initial C3, minimum C3, CH50, and greater changes in CH50 were associated with the normocoagulable phenotype." (PMID 38529277, 2024). "This agrees with Zinellu & Mangoni, 2021 who found low serum level of C3 and C4 suggesting more complement activation and product consumption, which is substantially associated with severe illness and higher mortality in COVID-19 patients." (PMID 39354444, 2024). "For this reason, people with C3 deficiency or hereditary angioedema with C1 inhibitor deficiency have often been seen to have asymptomatic or mild COVID-19." (PMID 37515137, 2023). "Our data demonstrate consumption of complement in acute COVID-19 patients reflected by low levels of C3, C4, and loss of haemolytic activity." (PMID 35572551, 2022). "Whilst in another study by our group from Hungary, we similarly measured complement in a cohort of 128 COVID-19 patients, and observed that higher C3a and C3a/C3 values were associated with increased risk of in-hospital mortality in COVID-19 patients." (PMID 35572977, 2022). "Meta-analysis of studies investigating systemic complement activation using serum samples of patients with COVID-19 demonstrated that lower C3 and C4 serum levels were significantly associated with higher COVID-19 severity and mortality." (PMID 35237273, 2022). "It has been recently demonstrated in humans that high levels of complement C3 were associated with persistent lung abnormalities in COVID-19 recovered subjects." (PMID 36232671, 2022). "Anemia, lower peripheral blood lymphocytes, monocytes, basophils, C3 Complement, cholesterol, and prothrombin time were also associated with COVID-19 after booster vaccination." (PMID 35632392, 2022). "In COVID-19, excessive activation of C3 and C5a have been linked to increased viral loads, coagulation, and lung injury." (PMID 35672453, 2022). "Most recently, the C3 inhibitor AMY-101 has been successfully used as treatment for a case of severe COVID-19–associated ARDS, perhaps by a similar mechanism." (PMID 34526511, 2021). "This study identified increased levels of complement C3 as a unique risk factor for adverse outcomes specific to young COVID-19 patients." (PMID 33846344, 2021). "In conclusion, lower concentrations of C3 and C4, indicating complement activation, were significantly associated with higher COVID-19 severity and mortality." (PMID 34163491, 2021). "In this report, we found that age, CK level, CD4 count, CD8 count, CD8 %, and C3 count were the independent risk factors for the progression of COVID-19." (PMID 32866109, 2020). "NETs are also associated with thrombotic events in COVID-19, consisting of platelets, complement (C3) and tissue factor in blood." (PMID 34192268, 2020). "Neutrophilia, lymphocytopenia, low CD4+ T cells, and decreased C3 were immunity-related risk factors predicting mortality of patients with COVID-19." (PMID 32746940, 2020). "Markers of complement activation, including elevated levels of C3, may provide insights into the underlying mechanisms contributing to prolonged COVID-19 symptoms." (PMID 40284924, 2025). "This could also be relevant, considering that it has been recently reported that low serum concentrations of C3 and C4 have been significantly associated with the presence of severe disease and increased mortality in patients with COVID-19." (PMID 40732912, 2025). "Furthermore, C3 overactivation and consumption (decrease in C3 concentrations and elevated ratio of C3a/C3) were identified as significant risk factors for COVID-19-related mortality." (PMID 37350773, 2023). "Interestingly, a retrospective cohort study showed that reduced levels of complement C3 were associated with poor prognosis in patients with COVID-19." (PMID 35288537, 2022).